TNF (tumor necrosis factor)
Diseases named in the same sentence as TNF in open-access papers (continued):
Sharing a sentence is not in itself a finding about the gene and the disease.
gastric ulcer (continued). "On the basis of energy values against different target proteins involved in gastric ulcer pathophysiology, the order of ligand affinity with the receptors was revealed as TNF-α > NFkB > H/K- > H+/K+ ATPase > COX-1 > COX-2 > M1 as compared to standard drugs." (PMID 36014311, 2022). "In the acetic acid-induced gastric ulcer rat model, orally administration of Zingiberis Rhizoma Recens aqueous extract (1.25, 2.5, and 5 g/kg) reduced the gastric ulcer area in dose-dependent manner via inhibiting the expression of the chemokines and TNF-α." (PMID 35645789, 2022). "In another murine model, intravenous nesfatin-1 alleviated gastric ulcers and reduced TNF-α and IL-1β by suppressing cyclooxygenase 2 signaling." (PMID 34389003, 2021). "Pro-inflammatory cytokines such as TNF-α and IL-1β play an important role in the pathogenesis of gastric ulcer." (PMID 34975468, 2021). "The gastroprotective effects of punicalagin (found in pomegranate juice) against an ethanol-induced gastric ulcer were confirmed to be achieved by reducing the protein expression of NF-kB, TNF-α gene expression." (PMID 33833690, 2021). "TNF-α is relevant to the inflammatory reaction, lipid metabolism, and apoptotic injuries in the development of gastric ulcer." (PMID 32325708, 2020). "Studies have shown that pro-inflammatory cytokines, such as TNF-α, IL-1β, and IL-6 play important roles in the formation of gastric ulcers." (PMID 33233494, 2020). "Diosmin showed gastroprotection (100 mg/kg, p.o.)against ethanol-induced gastric ulcers in rats, suppressed gastric inflammation, reducing TNF-α and NF-kB expression and restored levels of anti-inflammatory interleukin-10 (IL-10)." (PMID 33233494, 2020). "The administration of FL significantly lowered the gastric mRNA expression of inflammation-related genes, including NF-κb1, tumor necrosis factor-α, interferon γ, and prostaglandin-endoperoxide synthase 2, compared with the gastric ulcer control group." (PMID 32204312, 2020). "In the ethanol-induced gastric ulcer model, kaempferol, a flavanol from Kaempferia galanga L, decreased the plasma level of TNF-α by 33%, 43%, and 48%, and that of IL-1β by 46%, 43%, and 37% at doses of 40, 80, and 160 mg/kg, respectively." (PMID 33050668, 2020). "Solanum nigrum pretreatment significantly decreased TNF-α and IL-1β contents to 37.76% and 42.53%, respectively, in comparison to the gastric ulcer control group." (PMID 31731465, 2019). "Solanum nigrum pretreatment significantly decreased TNF-α and IL-1β contents in comparison to the gastric ulcer control group." (PMID 31731465, 2019). "TNF-α participates in gastric ulcer via promoting oxygen free radicals and enhancing apoptosis through the caspase cascade pathway and neutrophil migration into gastric mucosa facilitated by vessel congestion." (PMID 31827668, 2019). "Omeprazole pretreatment significantly decreased TNF-α and IL-1β contents to 59.88% and 48.38%, respectively, in comparison to the gastric ulcer control." (PMID 31731465, 2019). "Misoprostol pretreatment significantly decreased TNF-α and IL-1β contents to 46.90% and 40.26%, respectively, in comparison to the gastric ulcer control group." (PMID 31731465, 2019). "Althaea officinalis pretreatment significantly decreased TNF-α and IL-1β contents in comparison to the gastric ulcer control group." (PMID 31731465, 2019). "Misoprostol pretreatment significantly decreased TNF-α and IL-1β contents in comparison to the gastric ulcer control group." (PMID 31731465, 2019). "Chelerythrine reduced myeloperoxidase activity and nitric oxide concentration, pro-inflammatory IL-6 and TNF-α levels in ethanol-induced gastric ulcer mice at 1.5–10 mg/kg." (PMID 30018251, 2018). "TNF-α, an initiating proinflammatory cytokine, has a critical role in the pathogenesis of gastric ulcer via inflammation and injury inducement." (PMID 30116487, 2018).
gastric ulcer (continued). "Inevitably, alcohol resulted in the augmentation of the proinflammatory cytokines: TNF-α participating in gastric ulcer via boosting apoptosis, NF-κB, iNOS, and neutrophil infiltration and IL-1β arousing the oxidative stress inflicting the gastric damage." (PMID 30116487, 2018). "The inhibition of NF-κB is a primary mechanism for RI suppression of gastric ulcer since the expression of various pro-inflammatory cytokines including TNF-α is mainly regulated by the transcription of NF-κB." (PMID 29462911, 2018). "This phenomenon was initiated via the NF-κB pathway where the production of proinflammatory cytokines TNF-α and IL-1β, upregulation of iNOS gene expression, and release of NO were enhanced by activated NF-κB during gastric ulcer formation." (PMID 30116487, 2018). "TNF-α showed multifaceted function during gastric ulcer formation and activated NF-κB, iNOS, and neutrophil infiltration." (PMID 28587230, 2017). "In one rat model, ethanol-induced gastritis was found to progress into gastric ulcer as a result of apoptosis in the gastric mucosa stimulated by TNF-α overexpression." (PMID 29100443, 2017). "These proinflammatory cytokines were reported to play a very important role in ethanol-induced gastric ulcer formation, as TNF-α is an important modulator of gastric mucosal apoptotic cell death." (PMID 26770649, 2016). "The proinflammatory cytokine tumour necrosis factor-α (TNF-α) was found to play an important role in ethanol-induced apoptosis during gastric ulcer formation." (PMID 26770649, 2016). "TNF-α and IL-6 levels are increased in ethanol-induced gastric ulcers, but the harmful effect of these cytokines can be reversed by the administration of natural products with anti-inflammatory activity." (PMID 25954316, 2015). "It has been proposed that TNF-α and IL-6 are critical in controlling the graveness of gastric ulcer and the release of these cytokines can lead to the accumulation of ROS in the mitochondria resulting to oxidative stress." (PMID 26694339, 2015). "NF-κB activation and subsequent proinflammatory cytokine production, particularly TNF-α and IL-8, are evident in patients with gastric ulcer disease, especially those positive for H. pylori." (PMID 25610477, 2014). "It was suggested that the pro-inflammatory cytokines TNF-α and IL-6 are important in regulating the severity of gastric ulcers." (PMID 24466200, 2014). "Effect of menthol (50 mg/kg) on the levels of TNF-α, IL-6 and IL-10 cytokines in rat stomachs with ethanol-induced gastric ulcers after treatment with vehicle, carbenoxolone (100 mg/kg) or menthol (50 mg/kg)." (PMID 24466200, 2014). "TNF-α is a pro-inflammatory cytokine that is increasingly secreted by macrophages during gastric ulcer induction." (PMID 24466200, 2014). "In this study, we demonstrated that exogenous HMGB1 delays gastric ulcer healing, while inducing TNFα expression and MPO activity." (PMID 24244627, 2013). "The pro-inflammatory cytokines TNF-α and IL-1β have been shown to play an important role in the pathogenesis of gastric ulcer by initiating an early inflammatory process, while the regulatory cytokine IL-10 is known to attenuate TNF-α production." (PMID 23484048, 2013). "For example, our previous study demonstrated that TNFα over-expression and excessive neutrophil infiltration are complicating factors in the formation and healing of gastric ulcer." (PMID 24244627, 2013). "Administration of rHMGB1 at a dose of either 100 μg/kg or 1000 μg/kg significantly suppressed gastric ulcer healing, which was associated with increased MPO activity and TNFα mRNA expression in ulcerated tissues." (PMID 24244627, 2013). "Pentoxifylline, an inhibitor of TNF-α has been reported to accelerate healing of the acetic acid-induced gastric ulcers in rats possibly via inhibition of TNF-α production." (PMID 24192345, 2013). "To verify the anti-inflammatory effect of rosiglitazone on IND-induced gastric ulcer, we measured the serum level of TNF-α." (PMID 27990201, 2009).
gastric ulcer (continued). "If shown in other studies to have a physiological effect the association of ABO blood group with TNF-alpha levels could help the understanding of the mechanisms behind the associations between blood group O and a reduced risk of thrombotic related diseases but increased risk of gastric ulcers." (PMID 18464913, 2008). "Additionally, an animal study demonstrated that Saudi honey reduced TNF‐α in indomethacin‐induced gastric ulcers." (PMID 39957976, 2025). "In addition, it was reported that the anti-inflammatory effect of pioglitazone against gastric ulcer was through decreasing IL-1β, TNF-α and NO levels." (PMID 38441571, 2024). "Having confirmed that numerous biological agents able to diminish the levels of pro-inflammatory cytokines such as TNF-α, IL-1β, and IL-6, could potentially exhibit effectiveness in the management of gastric ulceration." (PMID 38355510, 2024). "CHE also significantly reduces the gastric ulcer index, inhibits NO concentration, IL-6 and TNF-α levels in serum and gastric mucosa of mice with gastric ulcers, while markedly attenuating the overexpression of NF-κB in the gastric mucosa to exert anti-inflammatory activity." (PMID 39239653, 2024). "The results confirmed that DOP was effective in reducing the levels of inflammatory factors (IL-1β, IL-6, and TNF-α) in the gastric tissues of rats with gastric ulcers, with the most significant effects observed in the DOP-200 and DOP-400 groups (p < 0.05 or p < 0.01)." (PMID 38398633, 2024). "Investigations focusing on gastric ulcers have consistently shown that probiotic administration leads to a reduction in gastric mucosal damage scores, lipid peroxidation, and levels of pro-inflammatory cytokine, like TNF-α." (PMID 38132119, 2023). "Dehydrocostus lactone could relieve ethanol-induced gastric ulcers in mice, which was considered to be related to the decrease in TNF-α, COX-2, and MDA and the increase in IL-10 and PCNA." (PMID 37109624, 2023). "Moreover, OM pretreatment improved indomethacin-induced gastric ulcer in rats where it decreased IL-6, TNF-α, and oxidative markers and improved mucosal contents of cyclooxygenase-1 and prostaglandin E2." (PMID 37255094, 2023). "Proinflammatory cytokines like TNF-α are critical in developing gastric ulcers." (PMID 37184667, 2023). "IFN-γ acts synergistically with TNF-α, triggering effects on gastric ulcers, including apoptosis, neutrophil infiltration, the release of oxygen free radicals, and other pro-inflammatory cytokines, leading to the destruction of cell membranes and gastric tissue." (PMID 35456589, 2022). "During gastric ulcers, macrophages produce TNF-α and delay the healing in several ways." (PMID 35456589, 2022). "Importantly, of all the proinflammatory cytokines, TNF-α retains diverse roles in the pathogenesis of gastric ulcers, including activation of neutrophil infiltration, apoptosis, NF-κB, and inducible nitric oxide synthase (iNOS)." (PMID 33521129, 2021). "During ethanol-induced gastric ulcer formation, NF-κB governs the increased transcription of genes encoding inducible nitric oxide synthase (iNOS), COX-2, and inflammatory cytokines including tumor necrosis factor-α (TNF-α), interleukin (IL)-6, and IL-1β." (PMID 34630623, 2021). "Indeed, IL-1β, IL-8, and PGE2 just like TNF-α promote the inflammatory response and are strongly involved in the development and maintenance of gastric ulcers in humans." (PMID 33354210, 2020). "Additionally, Althaea officinalis pretreatment significantly decreased TNF-α and IL-1β contents to 30.38% and 34.42%, respectively, in comparison to the gastric ulcer control group." (PMID 31731465, 2019). "Furthermore, ethanol provoked the gene expression of TNF-α, IL-1β, and iNOS, inflicting the immense effect of the generated NO on gastric ulcer formation." (PMID 30116487, 2018).
gastric ulcer (continued). "Furthermore, the serum proinflammatory cytokine IL-1β, IL-6, and TNF-α levels were significantly decreased following the administration of ethyl acetate extract of SP in a gastric ulcer model." (PMID 30116487, 2018). "Another possible mechanism by which manuka honey treats gastric ulcer may be due to inhibition of the proinflammatory cytokines: TNF-α, IL-1β, and IL-6." (PMID 28250794, 2017). "It is believed that drugs that could effectively treat or protect against gastric ulcer should have the ability to suppress the secretion of interleukin-6 (IL-6), tumor necrosis factor-alpha (TNF-α), scavenge ROS and/or stimulate mucosal defense mechanism." (PMID 26694339, 2015). "In brief, NF-κB and TNF-α is closely related to form and heal gastric ulcer." (PMID 24454691, 2014). "Thus, it is possible that HMGB1 delays gastric ulcer healing through TNFα-triggered inflammatory responses." (PMID 24244627, 2013). "Therefore, the present study was extended to evaluate the healing effects of MSE (test drug) in acetic acid-induced gastric ulcer in diabetic (DR-AA) rat and its effects on TNF-α, IL-1β and TGF-α." (PMID 24192345, 2013). "Moreover, gastric ulcer indices, histopathological morphology, oxidative stress markers (MDA, GSH, SOD), inflammatory mediators (NO, PGE2), and cytokine gene expression (TNF-α, IL-6, IL-1β, iNOS) were evaluated via enzyme-linked immunosorbent assay (ELISA) and quantitative real-time PCR." (PMID 40361682, 2025). "Compared with the control group, the expression levels of IL-1β, IL-6, and TNF-α in the gastric tissues of rats in the model group were significantly higher (p < 0.01), suggesting that the increased levels of inflammatory cytokines (IL-1β, IL-6, and TNF-α) were associated with gastric ulcers." (PMID 38398633, 2024). "Similarly, a study showed that administration of OLR at a dose of 500 mg/kg daily alleviates gastric damage and ulceration by the decrease of inflammation as tumor TNF-α, prostaglandin E2, endothelial nitric oxide synthase, and caspase-3 levels in indomethacin-induced gastric ulcer rat." (PMID 38911236, 2024). "However, the administration of OLE and OLR to gastric-ulcer rats protected from inflammation in gastric tissues and showed a potential decrease of TNF-α (by 21 and 17%, respectively) and IL-6 (54 and 47%, respectively) as compared to untreated gastric-ulcer rat." (PMID 38911236, 2024). "Therefore, by reducing TNF-α, IL-6, and IL-1β expression, A. graveolens may be considered as an alternative agent for treating gastric ulcer patients." (PMID 38355510, 2024). "Moreover, the high TNF-α levels found in gastric lesion specimens obtained from gastric ulcer patients strongly support the hypothesis that TNF-α has detrimental effects, including the induction of tissue injury and inflammation." (PMID 29849711, 2018). "Irbesartan reduced gastric ulcer index, gastric acidity, and ameliorated indomethacin-induced gastric mucosal apoptotic and inflammatory aberrations, as demonstrated by hampering caspase-3, prostaglandin E2 and tumor necrosis factor-alpha levels and cyclooxygenase-2 mRNA expression." (PMID 29523851, 2018). "For example, studies showed that Dioscorea administration in ethanol-induced gastric ulcer models significantly increased the activity of antioxidant enzymes such as SOD, GPx, and CAT, while reducing pro-inflammatory cytokines like TNF-α, IL-1β, and IL-6." (PMID 41010469, 2025). "Cheng, Lu & Yen (2017) reported that gastric ulcers have various processes such as the activation of phospholipase A, COX-2, myeloperoxidase (MPO), and pro-inflammatory cytokines (TNF-α, IL-6, and leptin)." (PMID 38435992, 2024). "Pretreatment with C. citrinus and OME-ameliorated gastric ulceration damage induced by IND, via anti-inflammatory mechanisms, by decreasing MPO, COX-2, and 5-LOX activities and inflammatory cytokines (TNF-α and IL-6)." (PMID 38435992, 2024).
gastric ulcer (continued). "In ethanol-induced gastric ulcers, CPC down-regulates the expression of NFκB and inflammatory cytokines such as IL-1β and TNF-α." (PMID 39000141, 2024). "TNFα overexpression and excessive neutrophil infiltration are important factors in delayed healing of gastric ulcers, while exogenous HMGB1 induces TNFα expression and Myeloperoxidase (MPO) activity." (PMID 39008169, 2024). "A separate study of a rat model of gastric ulcers reported that IND prompted an extensive inflammatory response with upregulated levels of both IL-6 and TNF-α." (PMID 37895164, 2023). "Omeprazole also decreased TNF-α levels; this indicates that adequate inhibition of stomach acidity by omeprazole repressed inflammatory reactions, which advised that acid may well improve mucosal inflammation layers in response to pro-inflammatory cytokines stimulus, subsequent in gastric ulcers." (PMID 38021520, 2023). "In gastric ulcer models, honey reduced the gastric mucosal malondialdehyde (MDA), IL-1β, IL-6, and TNF-α." (PMID 38045104, 2023). "Another in vivo study showed that supplementation with 10% pomegranate peel powder for 30 days increased nitric oxide in plasma and decreased gastric TNF-α and COX-2 gene expression in rats with aspirin-induced gastric ulcer." (PMID 36501143, 2022). "Meanwhile, chrysin activated peroxisome proliferator activated receptor-γ (PPAR-γ) and lowered the expression of pro-inflammatory marker genes, including TNF-α, IL-6, and CCL3, to fight indomethacin-induced gastric ulcer." (PMID 35008842, 2021). "Studies have shown that inflammatory factors such as pro-inflammatory cytokines TNF-α and IL-1β are significantly up-regulated and PI3K/Akt axis is activated in mice with gastric ulcer." (PMID 33841162, 2021). "Oral treatment with L-menthol decreased tumor necrosis factor-α (TNF-α), interleukin-6 (IL-6) levels, and increased interleukin-10 (IL-10) level in the rat model of gastric ulcers." (PMID 31827561, 2019). "BA-Zn (13 mg/kg) significantly accelerated the healing of gastric ulcers, through an increase in SOD and GSH-Px activity and a decrease in MDA, IL-8, and TNF-α contents." (PMID 30510570, 2018). "BA-Zn reduced the gastric ulcer index in a dose-dependent manner, significantly increased SOD activity and GSH-Px level, and reduced the MDA content and IL-8 and TNF-α levels in the gastric mucosa." (PMID 30510570, 2018). "In the present study, the serum levels IL-6, IL-12, TNF-α, and IFN-γ in the mice with reserpine-induced gastric ulcers were markedly decreased following treatment with insect tea." (PMID 25187847, 2014). "In a previous study, the colonic levels of IL-6, IL-12, TNF-α and IFN-γ in mice with reserpine-induced gastric ulcers were markedly decreased following D. candidum treatment." (PMID 25120640, 2014). "Serum HMGB1 levels increased following the induction of gastric ulcer but declined at the late phase of healing, although the expression of HMGB1 and TNFα remained high." (PMID 24244627, 2013). "This study investigated the effects of probiotics combined with quadruple therapy on serum levels of tumour necrosis factor-a (TNF-a), interleukin-6 (IL-6), C-reactive protein (CRP), gastrin (GAS), and motilin (MTL) in patients with Helicobacter pylori (Hp)-positive gastric ulcer (GU)." (PMID 41281280, 2025). "This study aimed to explore the clinical efficacy of probiotics plus quadruple therapy on Serum levels of tumour necrosis factor-a (TNF-a), interleukin-6 (IL-6), C-reactive protein (CRP), gastrin (GAS) and motilin (MTL) in treating Helicobacter pylori (Hp)-positive gastric ulcer (GU)." (PMID 41281280, 2025). "In addition, the supplementation of OLE or OLR to ethanol-induced gastric ulcer tats inhibits inflammation at the level of gastric tissues, observed by an important inhibition of MPO activity and TNFα and IL6 rates and improvement of NO rate." (PMID 38911236, 2024).